FOXA1 (forkhead box A1)
Description:
Transcription factor that is involved in embryonic development, establishment of tissue-specific gene expression and regulation of gene expression in differentiated tissues. Is thought to act as a 'pioneer' factor opening the compacted chromatin for other proteins through interactions with nucleosomal core histones and thereby replacing linker histones at target enhancer and/or promoter sites. Binds DNA with the consensus sequence 5'- [AC]A[AT]T[AG]TT[GT][AG][CT]T[CT]-3' (By similarity). Proposed to play a role in translating the epigenetic signatures into cell type-specific enhancer-driven transcriptional programs. Its differential recruitment to chromatin is dependent on distribution of histone H3 methylated at 'Lys-5' (H3K4me2) in estrogen-regulated genes. Involved in the development of multiple endoderm-derived organ systems such as liver, pancreas, lung and prostate; FOXA1 and FOXA2 seem to have at least in part redundant roles (By similarity). Modulates the transcriptional activity of nuclear hormone receptors. Is involved in ESR1-mediated transcription; required for ESR1 binding to the NKX2-1 promoter in breast cancer cells; binds to the RPRM promoter and is required for the estrogen-induced repression of RPRM. Involved in regulation of apoptosis by inhibiting the expression of BCL2. Involved in cell cycle regulation by activating expression of CDKN1B, alone or in conjunction with BRCA1. Originally described as a transcription activator for a number of liver genes such as AFP, albumin, tyrosine aminotransferase, PEPCK, etc. Interacts with the cis-acting regulatory regions of these genes. Involved in glucose homeostasis.
Synonyms: HNF3A; TCF3A
Tractability: No criterion of Open Targets' tractability assessment is met for any kind of drug.
Gene: Protein-coding gene on chromosome 14 (37,589,552 to 37,596,059, reverse strand). Ensembl gene ENSG00000129514.
Subcellular location: Nucleus
Subcellular location (Human Protein Atlas): Nucleoplasm; Nucleoli fibrillar center
Pathways (Reactome):
Developmental Biology: Formation of axial mesoderm
Signal Transduction: Estrogen-dependent gene expression
Gene Ontology:
Molecular function: DNA binding; protein binding; RNA polymerase II cis-regulatory region sequence-specific DNA binding; sequence-specific double-stranded DNA binding; transcription cis-regulatory region binding; DNA-binding transcription activator activity, RNA polymerase II-specific; DNA-binding transcription factor activity; DNA-binding transcription factor activity, RNA polymerase II-specific; chromatin binding; protein domain specific binding; sequence-specific DNA binding
Biological process: negative regulation of epithelial to mesenchymal transition; positive regulation of apoptotic process; positive regulation of intracellular estrogen receptor signaling pathway; positive regulation of mitotic cell cycle; positive regulation of transcription by RNA polymerase II; response to estradiol; anatomical structure morphogenesis; cell differentiation; chromatin remodeling; dopaminergic neuron differentiation; positive regulation of cell-cell adhesion mediated by cadherin; positive regulation of miRNA transcription; regulation of transcription by RNA polymerase II; regulation of DNA-templated transcription
Cellular component: fibrillar center; nucleoplasm; nucleus; chromatin; microvillus
Genetic constraint (gnomAD): Loss-of-function variants: 7 observed, 22.89 expected, observed/expected ratio (o/e) 0.31, 90% interval 0.17 to 0.57. The upper end of that interval is the gene's LOEUF score, 0.57, which puts it in group 2 of 6, group 1 being the genes least tolerant of losing a copy. Missense variants: 611 observed, 603.41 expected, observed/expected ratio (o/e) 1.01, 90% interval 0.95 to 1.08. Synonymous variants: 321 observed, 268.47 expected, observed/expected ratio (o/e) 1.2, 90% interval 1.09 to 1.31.
Cancer hallmarks: proliferative signalling (promotes); invasion and metastasis (suppresses)
Homologues: Orthologues: chimpanzee FOXA1 (99% identical), macaque FOXA1 (98% identical), mouse Foxa1 (95% identical), pig FOXA1 (94% identical), dog FOXA1 (93% identical), rat Foxa1 (93% identical), zebrafish foxa1 (62% identical). Paralogues in human: FOXA2 (56% identical), FOXA3 (38% identical), FOXC1 (23% identical), FOXC2 (23% identical), FOXD1 (21% identical), FOXD3 (21% identical), FOXD2 (20% identical), FOXJ3 (20% identical), FOXB1 (19% identical), FOXB2 (19% identical), FOXI3 (19% identical), FOXK2 (19% identical), and 29 more.
Diseases named in the same sentence as FOXA1 in open-access papers:
FOXA1 is named in the same sentence as 193 diseases in open-access papers, as found by Europe PMC text mining. Sharing a sentence is not in itself a finding about the gene and the disease. The quoted sentences say what the papers report.
breast carcinoma (433 papers, 2007 to 2026). "FOXA1 mutations are common in prostate and breast cancers, though their pathogenic mechanism is incompletely understood." (PMID 39633177, 2025). "Recent studies have highlighted the complex role of FOXA1 mutations in the response to endocrine treatments in breast cancer." (PMID 41224124, 2025). "Research has identified that the ability of colony formation, migration, and invasion of breast cancer cells caused by FOXA1 overexpression can be reduced by counteracting HIF-2α." (PMID 40003882, 2025). "A pioneering study analyzed chromatin immunoprecipitation followed by sequencing (ChIP-seq) data for TFs such as FOXA1 in multiple breast cancer cell lines, along with GWAS-identified risk variants." (PMID 39535029, 2025). "To validate the ER-independent role of FOXA1 triggered by heregulin, we examined the expression of genes associated with poor breast cancer prognosis." (PMID 41224124, 2025). "In breast cancer, FOXA1-driven enhancer reprogramming has been shown to activate HIF2α via super-enhancer engagement, thereby linking FOXA1 to hypoxia-associated oncogenic programs." (PMID 40643528, 2025). "Our study revealed that the genetic variations of 22 TFs were significantly associated with breast cancer risk and highlighted genetic variations of TF–DNA bindings (particularly for FOXA1) underlying breast cancer susceptibility." (PMID 39535029, 2025). "Genome-wide chromatin recruitment, chromatin openness, and transcriptional networks in breast cancer models with frequent FOXA1 mutations found that patients with these mutations had unique chromatin characteristics and did not respond well to AI therapy." (PMID 38605023, 2024). "Gene enrichment analysis revealed that genes linked to the cell cycle were downregulated by FOXA1-KD in T47D, highlighting the critical role of FOXA1 in cell proliferation in luminal breast cancer." (PMID 38429368, 2024). "As FOXA1 is seen to be mutated in other forms of cancer, such as breast cancer, mutational analysis of FOXA1 should be examined in this area as well." (PMID 38528115, 2024). "High expression of the FOXA1 gene was associated with worse overall survival in 2005 ER+/PR+ breast cancer patients from Kaplan–Meier plotter." (PMID 39000600, 2024). "Unsurprisingly, DESeq yielded DE genes previously known to be co-regulated with ER, such as GATA3 and FOXA1, since these genes are associated with the epithelial phenotype in ER-positive breast cancer cells." (PMID 39199676, 2024). "Overexpression or activating mutations of FOXA1 promote breast cancer aggressiveness and are associated with poorer outcomes." (PMID 38429368, 2024). "As in PCa, mutations of the pioneer transcription factor FOXA1 are common in ER+ breast cancer, and mutation of FOXA1 can alter its function and correlate strongly with endocrine therapy sensitivity." (PMID 38605023, 2024). "We further found that methylation and expression of FOXA1 is associated with parity and breastfeeding, suggesting a potential mechanism that links these reproductive exposures with ER- breast cancer among Black women." (PMID 37293596, 2023). "FOXA1 is a central regulator of gene expression programs in ER+ breast cancer, FOXC1 is associated with EMT and poor prognosis in basal-like breast cancer, and FOXO3 is often dysregulated and plays both tumor-suppressive and oncogenic roles." (PMID 37234983, 2023). "Knockout or downregulation of the transcription factor gene FOXA1 has also been linked to worse prognosis, altering the carcinogenic activity of the Snail/Twist1 axis in breast cancer as well as prostate cancer." (PMID 37895248, 2023). "FOXA1 mutations dysregulated estrogen-ER activity and were associated with worse outcome for metastatic ER + breast cancer." (PMID 37876590, 2023).
breast carcinoma (continued). "This has been observed in some of our data, as cBioPortal has only one TNBC patient with a FOXA1 mutation, compared to Breast Cancer Gene-Expression Miner v4.7, which has several TNBC patients with high or low expression." (PMID 36836779, 2023). "Previous studies have reported the mechanisms involved in inducing mutation in different genes, including those encoding FOXA1, ERα, or other ER coregulators, in ER+ breast cancer." (PMID 35453496, 2022). "In another breast cancer research, FOXA1 was found to downregulate EMT-associated markers, including E-cadherin, ZEB2, and vimentin, eventually preventing EMT progression." (PMID 36393971, 2022). "As a case example, we experimentally confirmed that FOXA1 knock-down is associated with higher methylation in regions bound by FOXA1 in breast cancer MCF-7 cells." (PMID 35440061, 2022). "For instance, a preliminary analysis that we performed on enhancer networks identified several genes with a burden of enhancer mutations, including FOXA1, in which promoter mutations are thought to drive breast cancer by increasing gene expression." (PMID 35726091, 2022). "The loss of KMT2C promotes breast cancer cell reprogramming by downregulating H3K4me1 and upregulating FOXA1-AP-1 binding." (PMID 35453496, 2022). "FOXA1 and ER are luminal-lineage TFs associated with breast cancer proliferation, progression, and drug resistance." (PMID 35676392, 2022). "FOXA1 is highly associated with breast cancer with a score of 5.8 and was identified as one of the master regulators of FGFR2." (PMID 35176995, 2022). "FOXA1 expression has been shown to be positively associated with estrogen receptor (ER)+ breast cancer." (PMID 36012038, 2022). "In breast cancer, FOXA1 and GATA3 are functionally linked with estrogen receptor alpha (ERα), and high level of expression of all three strongly correlates with the luminal subtype of breast tumors also referred as ER positive tumors (ER +)." (PMID 35331302, 2022). "These regulatory SNPs associated with altered chromatin loops in breast cancer were associated with pioneer factors (FOXA1, GATA3) and estrogen receptor." (PMID 35902807, 2022). "In ER breast cancer patients, FOXA1 hypermethylation is associated with the down-regulation of gene expression." (PMID 35178391, 2022). "Here, the authors develop a statistical framework to analyse ChIP-seq and GWAS data, identify 22 breast cancer risk-associated TFs and a core TF-transcriptional network for FOXA1 and co-factors." (PMID 34518541, 2021). "Stratified by FOXA1, the linear associations between breast cancer risk and TF scores of the other 21 TFs were significantly stronger in genetic variants occupied by FOXA1 than those not occupied by FOXA1 (P for interaction = 1.2 × 10−18)." (PMID 34518541, 2021). "Of them, the top risk-associated TFs included well-known breast cancer master regulators, FOXA1, ESR1, and AR, and other related TFs, such as SIN3AK and TCF7l2." (PMID 34518541, 2021). "Typically, there are 4 ‐ 5 copies (alleles) of FOXA1 in breast cancer cells, making the editing of this protein inherently challenging." (PMID 33666335, 2021). "Our findings provide additional insights into genetic variations of TF-DNA bindings (particularly for FOXA1) underlying breast cancer susceptibility." (PMID 34518541, 2021). "FOXA1 expression has been shown to positively associate with ER+ breast cancer, and its overexpression has been correlated with endocrine resistance via its capacity to trigger oncogenic gene signatures and pro-resistance proteomic profiles." (PMID 33669586, 2021). "The most recent breast cancer GWAS identified a 2–5 fold increased enrichment of risk SNVs in REs, mostly mapping to the binding sites for breast cancer–associated transcription factors including FOXA1, ESR1, GATA3, E2F1, and TCF7L2." (PMID 34439109, 2021).
breast carcinoma (continued). "Prior studies of HR+ breast cancer cells have demonstrated that the function of FOXA1 is impacted by the local enrichment of the histone variant H2A.Z." (PMID 34922480, 2021). "A recent examination of FOXA1 mutations in >4950 breast tumors and metastatic lesions found that 4.18% of breast cancers and 4.88% of metastases harbored recurring mutations, with the majority occurring in the Wing2 subdomain, consistent with previous reports." (PMID 34680352, 2021). "Class I missense and indel mutations are the most frequent FOXA1 mutations observed in breast cancer." (PMID 34680352, 2021). "It found that breast cancer risk-associated regulatory SNPs modulated the binding affinity of FOXA1 and altered gene expression." (PMID 34518541, 2021). "Of note, there are multiple copies of FOXA1 in breast cancer cells (typically 4–5 alleles) making the editing of this protein inherently challenging." (PMID 33666335, 2021). "FOXA1 missense mutations are enriched in metastatic luminal breast cancers compared to primary lesions and are often mutually exclusive with mutations in ESR1." (PMID 34680352, 2021). "In brief, the altered expression pattern of FOXM1/GATA3/FOXA1/ESR1-associated lncRNAs in breast cancer suggests future assessment of the functional role of these genes in the development of breast neoplasms." (PMID 34094972, 2021). "High FOXA1 was associated with better breast cancer specific survival among ER-positive breast cancer." (PMID 32241272, 2020). "The hotspot mutation in the FOXA1 promoter region, in addition to mutations within the coding sequence, has been reported in breast cancer and leads to the overexpression of FOXA1 through increased E2F binding." (PMID 32235312, 2020). "In conclusion, we report here that the stem cell pluripotency factor Sox2 is commonly expressed in feline mammary carcinomas, is associated with higher proliferation, decreased PR and FOXA1, but higher AR expression, as well as poor outcomes." (PMID 33553286, 2020). "Further, similar to findings in prostate cancer, 1.8% of breast cancers harbor mutations in FOXA1, and amplifications of the FOXA1 gene locus have been observed in breast and prostate cancers." (PMID 33062889, 2020). "At present, most studies on the FOXA1 gene polymorphism revolve around type 2 diabetes and breast cancer." (PMID 32411194, 2020). "GATA3 and FOXA1 are mutated in a mutually exclusive manner, which suggests that a mutation in FOXA1 would also mark a breast cancer that is endocrine therapy sensitive." (PMID 31281796, 2019). "The significance of FOXA1 expression appears to be similar in human oncology, as FOXA1 positivity of breast carcinomas is associated with better outcomes especially in luminal carcinomas." (PMID 31888566, 2019). "As determined using cBioPortal, the FOXA1 mutation frequency was less than 8% in patients with breast cancer." (PMID 31562808, 2019). "In breast cancer metastases, FOXA1 expression was associated with Nestin-negativity, GATA3-positivity, ER-positivity, HER2-positivity and non-triple-negative status (P < 0.05)." (PMID 30819139, 2019). "FOXA1 positivity in FMCs was negatively associated with pathologic nodal stage, including in triple-negative FMCs, as reported in human breast cancer." (PMID 31888566, 2019). "The expression of the transcription factor FOXA1 is associated with the prognosis of estrogen receptor (ER)-positive breast cancer, and the genetic variant rs4442975 can affect FOXA1 function." (PMID 30881995, 2019). "Overall, we found that as in human breast cancer, FOXA1 positivity in FMCs was associated with favorable features such as negative nodal stage, lower clinical stage, lower histological grade and lower proliferation index." (PMID 31888566, 2019). "FOXA1 positivity has also been linked with a more favorable prognosis in breast cancer patients treated with Tamoxifen." (PMID 30819139, 2019).